GPC3 (glypican 3)
Diseases named in the same sentence as GPC3 in open-access papers (continued):
Sharing a sentence is not in itself a finding about the gene and the disease.
liver cancer (continued). "Making use of this distinct feature of GPC3 in HCC, an anti-GPC3 antibody therapy or antibody-drug conjugate (ADC) could be used as a biological missile targeting the GPC3-expressing cells, including liver cancer cells and CD90+CSCs." (PMID 22606345, 2012). "However, single anti-GPC3 antibody therapy does not kill liver cancer altogether, which may need to achieve high target saturation in tumor cells to induce any beneficial effect." (PMID 35251989, 2022). "Therefore, we generated an animal model of liver cancer by injecting mouse with CCl4 and then excised tissue samples from the mouse at the three typical stages of HCC progression (liver fibrosis, liver cirrhosis, and HCC) for immunofluorescence staining of GPC3 and ARG1." (PMID 35331259, 2022). "For example, Glypican-3 (GPC3), a member of the heparan sulfate proteoglycans family, is one of the top contributing genes in liver cancer but not in normal liver." (PMID 35931322, 2022). "In these samples, both GPC3 and ARG1 were expressed in the liver cancer tissue but not in normal liver tissue, and the expression of GPC3 or ARG1 in HCC tissue were higher than that in normal tissue." (PMID 35331259, 2022). "Glypican-3 (GPC3), another GPI-anchored protein, is highly expressed in most liver cancers, but absent or expressed at very low levels in normal adult tissues." (PMID 32184825, 2020). "Additionally, the genes that are distinctly expressed in liver CD90+CSCs but not in CD90+NTSCs, such as GPC3, could be promising candidates for immunotherapy, which could eliminate liver cancer stem cells and adult cancer cells without inducing damage to normal liver cells." (PMID 22606345, 2012). "However, the efficacy of the combination of AFP + MDK, GPC3 + OPN has not been determined yet; therefore, significance of the combined use of these tumor markers in the diagnosis of liver cancer should be investigated in the near future." (PMID 34513063, 2021). "Glypican-3 (GPC3), a member of the glypican family, is anchored by glycosylphosphatidylinositol (GPI), and highly expressed in most liver cancers, but it is absent or expressed at very low levels in normal adult tissues." (PMID 29916268, 2018). "The immunostains for intrinsic liver cancer markers AFP, Hep Par 1 and GPC3 were all negative." (PMID 28955934, 2016).
melanoma (42 papers, 2010 to 2025). A malignant, usually aggressive tumor composed of atypical, neoplastic melanocytes. "Specific tumor-associated antigens including glypican-3 and survivin are markers for melanoma and many cancer cell types." (PMID 21689407, 2011). "Reports demonstrate that the upregulation of proteoglycans such as glypican-3 significantly contributes to the pathogenesis of several melanoma types." (PMID 35628212, 2022). "GPC-3 has also been reported to enhance the proliferation of nephroblastoma, hepatoblastoma, and melanoma cells." (PMID 34715880, 2021). "AFP and Glypican-3 are less sensitive but somewhat more specific oncofetal markers (Glypican-3 can be expressed in some melanomas)." (PMID 29621151, 2018). "With the exception of HCC and melanoma, GPC3 was also expressed in other human malignancies, and has been reviewed in another article." (PMID 30135409, 2018). "The inhibitory receptor PD-1, was upregulated in GPC3-specific CTLs of HCC patients vaccinated using GPC3 peptide, consistent with previous reports of melanoma vaccine trials." (PMID 25354479, 2015). "GPC3 is also overexpressed in other malignant tumors, such as melanoma, Wilms’ tumor, hepatoblastoma, yolk sac tumor, ovarian CCC and lung squamous cell carcinoma." (PMID 25189159, 2014). "Mice vaccinated with DC expressing GPC-3 as a transgene were also found to have protective immunity against subsequent challenge with GPC-3 positive melanoma cells." (PMID 20465843, 2010). "However, in melanoma, the role of GPC3 as an oncogene or a tumor suppressor remains controversial despite its up-regulated expression." (PMID 40422229, 2025). "The upregulation of proteoglycans such as glypican-3 leads to the development of melanoma." (PMID 35959427, 2022). "Glypican-3 is positive in 65–80% of HCCs, more often in poorly differentiated than well differentiated tumors; however, glypican-3 may also be positive in a variety of other malignancies, such as carcinomas from other sites, melanoma, and germ cell tumors." (PMID 35954333, 2022). "The therapeutic effects of GPC3 knockdown on melanoma metastasis could include the additive or synergistic effects of controlling not only cancer cells but also immune cells, because GPC3 is particularly involved in cancer cell growth, migration, infiltration, and in immune responses." (PMID 35456649, 2022). "SDC3 is specifically increased in melanoma and brain tumors, but SDC2 and GPC3 are up-regulated in HCC." (PMID 35850748, 2022). "Overexpression of GPC3 has been reported in some types of cancer such as HCC, melanoma, squamous cell carcinoma of the lungs and testicular germ cell tumors." (PMID 25896897, 2015). "GPC-3 (also called DGSX, GTR2-2, MXR7, OCI-5, SDYS, SGB, SGBS, and SGBS1), a cell exterior protein, is extremely expressed in HCC and some other human cancers including melanoma." (PMID 22087135, 2011). "Glypican-3 (GPC3), however, is overexpressed in melanoma and its serum concentration can serve as an early stage melanoma diagnostic marker." (PMID 20479946, 2010). "In addition, PSME2 and other four gene markers for malignant cells (ARID5A, SERPINE2, GPC3, and S100A11) were combined to develop a prognostic signature in melanoma." (PMID 36583022, 2022). "To date, GPC-3 is the most well-documented GPC gene in its family in different cancers, including HCC, ovarian clear cell carcinoma, melanoma, squamous cell carcinoma of the lung, hepatoblastoma, nephroblastoma (Wilms tumor), yolk sac tumor, and some pediatric cancers." (PMID 33902495, 2021). "GPC3 protein expression is elevated in several neoplastic tissues including melanoma compared to nonneoplastic and normal tissues." (PMID 31199813, 2019). "However, GPC3 was highly expressed in other tumours, such as HCC, Wilms’ tumour and neuroblastoma, hepatoblastoma and melanoma, as well as lung SCC." (PMID 31160489, 2019).
melanoma (continued). "Unfortunately, not all HCC cells express GPC3, while increased GPC3 expression is also found in squamous cell- and lung-carcinomas, clear cell tumors of the ovary, testicular germ cell tumors and melanomas." (PMID 32443747, 2020). "GPC-3 is also positive in melanoma and nonseminomatous germ cell tumors such as choriocarcinoma." (PMID 24281095, 2010). "GPC3 is expressed in the placenta, numerous embryonic tissues, and various tumors such as HCC but not in the healthy adult liver, ovarian carcinoma, and melanomas." (PMID 37932427, 2023).
ovarian carcinoma (41 papers, 2012 to 2025). A malignant neoplasm originating from the surface ovarian epithelium. "One research from Switzerland showed GPC3 was expressed in a total of 17.9% of ovarian carcinomas and was strongly associated with the clear-cell histotype (P = 0.0001)." (PMID 38824600, 2024). "As a tumor-associated antigen, induction of immune response of GPC3 in ovarian cancer remains elusive." (PMID 24992906, 2014). "GPC3 expression is often silent or decreased in ovarian cancer except clear cell carcinoma types, as well as in mesothelioma, breast cancer, lung adenocarcinoma, and clear cell renal carcinoma." (PMID 40422229, 2025). "In ovarian cancer, cells that exhibit resistant to platinum-based chemotherapeutic drugs tend to express lower levels of GPC3, suggesting a negative regulatory role for GPC3 in the development of drug resistance." (PMID 40422229, 2025). "Conversely, GPC3 expression is down-regulated in certain types of cancers, such as ovarian cancer, cholangio-carcinoma, gliomatosis cerebri, and mesothelioma, where it appears to function as a tumor suppressor." (PMID 40422229, 2025). "Others: GPC3 knockdown in ovarian cancer cells can lead to an increase in the expression of matrix metalloproteinase 2 (MMP-2) and MMP-9, along with a decrease in the level of tissue inhibitors of metalloproteinase 1 (TIMP-1)." (PMID 40422229, 2025). "TGF-β-signaling pathway: In ovarian cancer cells, the down-regulation of GPC3 expression by RNA interference has been shown to elevate the levels of TGF-β2 protein, accompanied by the increase in cell proliferation and tumor growth in vivo." (PMID 40422229, 2025). "A phase I clinical trial was conducted on advanced HCC/PC/ovarian carcinoma patients with glypican-3 (GPC3) or MSLN expression (NCT03198546)." (PMID 38727261, 2024). "Upregulation of miR‐1228‐5p, miR‐193a‐5p and miR‐375‐3p predicted the response to GPC3 vaccine in patients with ovarian carcinoma." (PMID 37735815, 2023). "In ovarian carcinoma patients, researchers conducted an investigation into circulating serum biomarkers to monitor treatment response following administration of the GPC3 peptide vaccine." (PMID 37735815, 2023). "initiated a Phase I clinical investigation to evaluate the safety and applicability of these CAR-Ts in individuals with ovarian cancer (proficient in the expression of glypican 3 or mesothelin), as well as other advanced solid tumors (NCT03198546)." (PMID 38146364, 2023). "Further, Ueda and colleagues transduced an anti-glypican-3 (GPC3) CAR, targeting GPC3 that is expressed in liver and ovary cancers but rarely in healthy tissue, into iPSCs." (PMID 37514187, 2023). "These researchers also reported the early results of an ongoing Phase I clinical trial (NCT03198546) in patients with advanced HCC, pancreatic carcinoma, or ovarian carcinoma who have glypican-3 (GPC3) or mesothelin expression." (PMID 35634281, 2022). "A similar pattern of GPC3 downregulation was also detected in other tumours, such as mesotheliomas and ovarian cancer." (PMID 36676710, 2022). "We then initiated a phase 1 clinical trial in advanced HCC/PC/ovarian carcinoma (OC) patients with glypican-3 (GPC3) or mesothelin (MSLN) expression." (PMID 34325726, 2021). "Specifically, GPC3 has been reported to be expressed at low levels in ovarian carcinoma, mesothelioma and breast carcinoma tissues compared with normal tissues." (PMID 31160489, 2019). "GPC3 (glypican 3), a member of the heparan sulfate proteoglycans, has been widely studied as a target in human cancer, such as ovarian carcinoma." (PMID 32047514, 2019). "Contrarily, down-regulation of GPC3 in ovarian cancer and breast cancer promotes tumor migration and invasion." (PMID 31199813, 2019). "GPC3 induces apoptosis in ovarian cells, suggesting that it plays an important role in the development of ovarian cancer." (PMID 32047514, 2019).
ovarian carcinoma (continued). "Glypican-3 (GPC3) enhances M1 macrophage recruitment and increases the secretion of IL-12 and TNF-alpha in ascites of GPC3 expressing mouse models of ovarian cancer." (PMID 30274280, 2018). "Supporting these results, it was reported that overexpression of GPC3 in renal carcinoma and in ovarian cancer cell lines, reduced their clonogenic efficiency." (PMID 27507057, 2016). "The expression levels of GPC3 are down-regulated to facilitate cell migration, invasion and tumorigenicity in ovarian cancer." (PMID 27769251, 2016). "Glypican-3 expression is reduced in the progression of cancers that originate from GPC3-positive tissues, such as ovarian cancer and mesothelioma." (PMID 26517809, 2015). "Downregulation of glypican-3 has been described in many tumor types, including breast, lung, gastric, and ovarian cancers and mesothelioma." (PMID 26482785, 2015). "In several malignant tumors, including ovarian carcinoma, cholangiocarcinoma, mesothelioma, and breast cancer, GPC3 is down-regulated as a result of hypermethylation of the GPC3 promoter." (PMID 26517809, 2015). "GPC3 is demonstrated to induce T cell-mediated immune response in HCC; however, it is unclear in GPC3 expressing ovarian cancer." (PMID 24992906, 2014). "Downregulation of GPC3 has been described in many tumor types, including breast, lung, gastric, and ovarian cancers and mesothelioma." (PMID 24570896, 2014). "GPC3 is frequently silent in ovarian cancer cell lines and seems to play as a tumour suppressor in ovarian and lung cancer." (PMID 24804215, 2014). "Our results demonstrated that GPC3 expression induced T cell-mediated immune response in this mouse ovarian cancer model and also provided supportive evidence that GPC3 is an ideal target for ovarian cancer immunotherapy." (PMID 24992906, 2014). "We obtained a result that GPC3 on mouse ovarian cancer cells induces CD86 expression on mouse intraperitoneal macrophages." (PMID 24992906, 2014). "GPC-3 show different behaviors among different cancers, while it has been reported to be downregulated in breast cancer, ovarian cancer and lung adenocarcinoma, it has been reported to be upregulated in HCC." (PMID 23162601, 2012). "The researchers hypothesize that the increase in TGF-β2 expression contributes to the growth of tumors derived from GPC3 knockdown in ovarian cancer cells." (PMID 40422229, 2025). "The imbalance of MMPs and TIMP-1 might contribute to the enhanced motility and invasion observed in ovarian cancer cells with GPC3 knockdown." (PMID 40422229, 2025). "For instance, data from the cancer RNAseq database indicate that GPC3 mRNA levels are diminished in breast, kidney, lung and ovarian cancers when compared to their normal counterparts, yet a stark contrast is observed in HCC where GPC3 levels are markedly elevated relative to normal liver tissues." (PMID 40422229, 2025). "[89Zr]Zr-ERY974, a bsAb targeting CD3ε on T-cells × GPC3, showed high specific uptake in GPC3-positive ovarian cancer xenografts ingrafted with immune cells compared to xenografts in immunodeficient mice, highlighting the potential value of such probes in immunotherapy response monitoring." (PMID 35836956, 2022). "In our previous study, we discovered the utility of GPC3 knockdown in ovarian cancer." (PMID 35456649, 2022). "Notably, CAR NK/ILC were capable to elicit cytotoxic response against GPC3 expressing tumor cells, and prolonged survival when injected into mice with ovarian cancer." (PMID 34367185, 2021). "GPC3 is downregulated in breast, lung and ovarian cancers, and it may act as a tumor suppressor in lung and renal cancer." (PMID 31956905, 2020). "Therefore, we used this mouse ovarian cancer model to analyze the effect of GPC3 on ovarian cancer immune microenvironment." (PMID 24992906, 2014). "In addition, as a result of F4/80+CD86+ macrophage increase in GPC3-expressing mouse ovarian cancer, we analyzed the effect of GPC3 on CD86 expression in mouse intraperitoneal macrophages." (PMID 24992906, 2014).
ovarian carcinoma (continued). "Finally, in order to confirm that this immune response suppresses GPC3-expressing tumor growth, we used the intraperitoneal ovarian cancer mouse model to investigate the effect of GPC3 on mouse survival rate." (PMID 24992906, 2014). "In conclusion, the present study demonstrates that GPC3 expression induces T cell-mediated immune response in this mouse ovarian cancer model and also provides supportive evidence that GPC3 is an ideal target for ovarian cancer immunotherapy." (PMID 24992906, 2014). "Therefore, we used the intraperitoneal GPC3-expressing ovarian cancer mouse model to examine macrophage distribution in tumor with a mouse F4/80 monoclonal antibody." (PMID 24992906, 2014). "Kaneko’s group used HLA-homozygous iPSCs to derive NK cells expressing a GPC3-CAR, demonstrating efficacy for the treatment of GPC3+ ovarian cancer." (PMID 41465318, 2025). "Glypican-3, ALDH1A1, TNFR2, STAT3, FOXP3, and TIM3 are increasingly recognised biomarkers to predict chemoresistance in women with ovarian cancer." (PMID 36768291, 2023). "Elevated expression levels of SDC3 have been reported in bladder and ovarian cancer, and renal cell carcinoma, whereas low levels of SDC3, SDC4, GPC1, and GPC3 are expressed in neuroblastoma." (PMID 32916872, 2020). "GPC3 and GPC4 have been downregulated in oxaliplatin-resistant ovarian carcinoma cell line A2780/C10." (PMID 24804215, 2014). "We established a GPC3 transgenic mouse ovarian cancer cell line, OV2944-HM-1 (HM-1), and used the intraperitoneal ovarian cancer mouse model to investigate immune response in GPC3-expressing tumor." (PMID 24992906, 2014). "This is because the GPC3 peptide vaccine is not yet a standard treatment for ovarian cancer, and the study sample was obtained from limited and valuable samples in the phase II study of the GPC3 peptide vaccine." (PMID 33535558, 2021). "GPC3 mediates the synthesis of integral membrane proteins that interact directly with insulin like growth factor 2 (IGF2), which is considered to be an important growth factor in ovarian cancer." (PMID 32047514, 2019). "Studies in ovarian cancer cell lines uncover that the silencing of GPC3 is regulated epigenetically rather than through genetic mutations." (PMID 27259271, 2016). "Therefore, we used mouse GPC3, which shares 95% amino acid sequence identity with human GPC3, established a GPC3 transgenic mouse ovarian cancer cell line, OV2944-HM-1 (HM-1), and used the intraperitoneal ovarian cancer mouse model to analyze immune response in GPC3-expressing mouse ovarian cancer." (PMID 24992906, 2014). "Previous studies have indicated that GPC3 expression is predominantly restricted to certain malignancies such as HCC, ovarian cancer, and yolk sac tumors, with limited or no expression in cancers originating from the gut or lung." (PMID 41465318, 2025).